KEAP1 (kelch like ECH associated protein 1)
Diseases named in the same sentence as KEAP1 in open-access papers (continued):
Sharing a sentence is not in itself a finding about the gene and the disease.
cancer (continued). "Keap-1 knocked-down amplified M2-macrophages induction by cancer cells, appearing as decreased IL-1b and IL-6 expression, and increased CD163 and Arg1 expression." (PMID 30180849, 2018). "Indeed, the Nrf2/Keap1 pathway is activated by quercetin, fisetin, piperlongumine, and phloretin as well as by different cannabinoids, tocotrienols, and a multitude of anticarcinogenic natural compounds that were found to cause cancer cell apoptosis or senescence under certain conditions." (PMID 29618945, 2018). "In contrast, "constitutive" Nrf2 activation and dysregulation of the Keap1–Nrf2 pathway, as well as accumulation of p-p62 and high Nrf2 expression, were observed in certain cancer cells." (PMID 29241092, 2018). "We will not consider the few chalcones that show an ability to inhibit or modulate the Keap1/Nrf2–ARE pathway in cancer prevention and therapy." (PMID 30037040, 2018). "An intriguing epigenetic way of KEAP1/NRF2 pathway deregulation in tumor cells comes from miRNAs that act in cancer as oncogenes or tumor suppressors." (PMID 29643973, 2018). "In order to further investigate the role of p62 for chemotherapy response, we additionally compared the expression of some downstream proteins (NRF2/KEAP1) and NF-κB in both primary resected and neoadjuvantly treated carcinomas." (PMID 29897944, 2018). "It has been reported that cancer cells upregulate the KEAP1/NRF2 pathway to adapt to high levels of ROS and to the subsequent oxidative stress." (PMID 28981199, 2017). "First, somatic mutations within the NRF2, KEAP1, or CUL3 genes have been shown to cause aberrant NRF2 activation in cancer cells." (PMID 28523248, 2017). "Many types of cancer exhibit aberrant levels of Nrf2, as a result of the dysregulation of the Keap1-Nrf2 pathway." (PMID 29261130, 2017). "All these molecular events result in disrupted binding of KEAP1 to NRF2, causing aberrant accumulation of NRF2 in cancer cells." (PMID 28523248, 2017). "Altogether, the combinatorial analysis suggested a good level of agreement that KEAP1/NRF2 plays an important role in various metabolic functions in cancer cells." (PMID 29050246, 2017). "As in some other cancer types, a significant fraction of UC contain mutations in the NFE2L2 gene, typically missense mutations in the Neh2 domain required for KEAP1 interaction that are expected to cause NRF2 overexpression." (PMID 28767070, 2017). "KEAP1 has been the most highly studied regulator of NRF2, as mutations in KEAP1, which result in uncontrolled activation of NRF2 and chemo-resistance, are found in many aggressive cancers." (PMID 28453520, 2017). "Despite the chemopreventive action of NRF2, growing evidence suggests that mutations in KEAP1 and/or NRF2 cause the aberrant activation of NRF2, which leads to oncogenesis and drug resistance in cancer cells." (PMID 29050246, 2017). "In support of our finding that WDR23 negatively regulates NRF2, several of these cancer cells with mutations in WDR23 have increased expression of NRF2 targets, but have normal KEAP1." (PMID 28453520, 2017). "The nuclear protein level of Keap1 is reduced, resulting in nuclear Nrf2 stabilization and its transcriptional activity increases in cancer cells, which contributes to tumor cell resistance to chemotherapy." (PMID 28501854, 2017). "In this review, we will focus on the regulation of cellular NRF2 levels by KEAP1 and the perturbation of KEAP1 regulation in cancer cells." (PMID 28523248, 2017). "Genetic alterations of KEAP1 or NFE2L2 (Nrf2 gene) in cancers, especially in lung cancers, are also uncovered by large-scale omic project." (PMID 27200299, 2016).
cancer (continued). "Another interesting aspect is that the occurrence of KEAP1 and NRF2 mutations is mutually exclusive in cancer patients, suggesting that targeting either KEAP1 or NRF2 is sufficient to activate ARE-dependent gene expression in cancer." (PMID 27340506, 2016). "This conjecture is supported by epidemiological observations that KEAP1 and NRF2 are abundantly mutated in various types of human cancer." (PMID 27340506, 2016). "Nrf2 expression is maintained at low basal levels by constant degradation by the ubiquitin- (Ub-) proteasome pathway (UPP) under quiescent conditions; however, in cancer cells harboring dysfunctional Keap1, such as A549 cells, Nrf2 is constitutively activated." (PMID 26904167, 2016). "Although the chemopreventive function of Keap1–Nrf2 pathway protects normal cells from carcinogenesis, once tumor is formed, cancer cells hijack this pathway for acquiring survival and growth advantage to cope with stressed conditions." (PMID 27200299, 2016). "Numerous studies have shown that the Nrf2/Keap1 system can protect normal cells from exogenous ROS, but promotes the death of cancer cells under deleterious conditions." (PMID 27029077, 2016). "The results showed that preserved cytoplasmic Keap1 expression of cancer cells was observed in 59 HCCs, while reduced Keap1 expression was determined in remaining 48 ones." (PMID 27650414, 2016). "As an alternative approach, we also cloned and overexpressed individually both NRF2 and KEAP1 genes in our cancer cell lines and found these in either cytoprotection or sensitisation to targeted therapies, respectively (data not shown)." (PMID 26770651, 2016). "A recent study indicates that Keap1 degradation was critical for activation of the Nrf2 signaling pathway, a major defense mechanism in cancer cells." (PMID 27650414, 2016). "In particular, we will focus on three Cul3 substrate adaptors, kelch-like ECH-associated protein (Keap1), kelch-like family member 20 (KLHL20), and speckle type BTB/POZ protein (SPOP), with the intent to highlight novel targets in cancer therapy." (PMID 27200299, 2016). "Core components of the pathway itself are some of the most frequently mutated genes in cancer, with mutations in NRF2 and KEAP1 occurring in diverse tumour types." (PMID 27824809, 2016). "According to all these recent findings, the Keap1‐Nrf2 system plays a crucial role in cellular defense against oxidative stress, which has been reported to promote cancer development and act as a biomarker to anticipate prognosis of HCCs." (PMID 27650414, 2016). "A similar chemoresistant phenotype is found in cancer cells with elevated Nrf2 activity due to reduced Keap1 expression." (PMID 27200299, 2016). "Keap1 expression was significantly decreased in the cytoplasm of cancer cells compared with that of normal cervical epithelial cells (P<0.05)." (PMID 26247201, 2015). "It has been shown that many polyphenols gain their beneficial properties (e.g. cancer prevention) through the activation of the Nrf2/Keap1 pathway as well as their direct antioxidant activity." (PMID 25498967, 2015). "The mechanisms are similar to that in the cancer chemo-preventive and anti-inflammation effect, as are result of Keap1 alkylation and the resulting activation of antioxidant enzymes are also involved." (PMID 25574819, 2015). "Keap1 appears, through controlling Bcl-2 expression levels, to function as a molecular sensor to regulate apoptosis in cancer cells harboring oncogenic ras." (PMID 26041886, 2015). "In conclusion, this study adds data to the growing knowledge that highlights the importance of Keap1/Nrf2 pathway in human carcinomas." (PMID 25879528, 2015). "This condition decreases Keap1 expression and upregulates the Nrf2 expression resulting in removal of ROS and protection of cancer cells." (PMID 25988128, 2014). "Further analysis is also necessary to understand the regulation of the Nrf2/Keap1 pathway in cancer treatment with autophagy inducers or inhibitors." (PMID 24681637, 2014).
cancer (continued). "The purpose of MitoQ-induced autophagy in cancer cells is to activate the Keap1/Nrf2 pathway and reduce oxidative stress." (PMID 24681637, 2014). "Gain-of-function mutations in NFE2L2 and inactivating KEAP1 mutations are the most frequent NRF2 activation mechanisms observed in breast, gallbladder, and lung tumors, among other cancer types." (PMID 25114896, 2014). "Four KLHL family members are associated with cancer: KLHL6, KEAP1 (KLHL19), KLHL20, and ENC1 (KLHL37)." (PMID 23676014, 2013). "Mutations in Nrf2 and Keap1 that are predicted to disrupt their interactions are found in many human cancers, suggesting that Nrf2 interactions with Keap1 counteract cancer progression." (PMID 23408904, 2013). "Another effective approach to increasing cancer cell sensitivity to chemotherapeutic drugs would be to silence both Nrf2 and Keap1 simultaneously." (PMID 23766865, 2013). "While another Keap1 substrate, Nrf2, has been known as an attractive target for chemprevention of cancer." (PMID 24066166, 2013). "Nrf2 and Keap1 are investigated as potential targets for therapeutic interventions in cancer, neurodegenerative diseases and developmental disorders." (PMID 23408904, 2013). "In fact, the Keap1–Nrf2 pathway plays in the protection of our body against drug toxicity and stress induced diseases, and cancer cells hijack Nrf2 activity to support their malignant growth and thus Nrf2 has emerged as a therapeutic target." (PMID 24386210, 2013). "The role of NRF2 and KEAP1 in cancer development has been highly controversial and has led to many theories including NRF2 as an oncogene, or its manipulation by an oncogene, specifically in the lung." (PMID 23577226, 2013). "In this review, we provide an overview of the Keap1–Nrf2 system and discuss its role under physiological and pathological conditions, including cancers." (PMID 23272301, 2012). "Further studies show various genetic abnormalities of the Nrf2 repressor, Keap1, in several cancer cell lines and tumor tissues, including GC." (PMID 22901367, 2012). "Decreased Keap1 activity in these cancer cells induced greater nuclear accumulation of Nrf2 and constitutive over expression of ARE-containing genes including MRP, NQO1 and GCL." (PMID 24212776, 2011). "Under a hypoxia/reoxygenation condition, which mimics tumour microenvironment, Keap1 expression is decreased whereas Nrf2 and peroxiredoxin-1 (Prx1) up regulated, resulting in removal of ROS and protection of cancer cells." (PMID 24281078, 2010). "Thus far, we have examined immune cell infiltration by using bilateral transplantations of WT and KEAP1-KO 3LL cancer cells to albino C57BL/6 mice." (PMID 41035689, 2025). "Many cancers exploit the KEAP1/NRF2 pathway through genetic alterations." (PMID 39859211, 2025). "Similarly, in a Japanese cohort of 60,056 cancer patients, 1.7% and 2.5% carried mutations of NRF2 (exon 2) and KEAP1, respectively." (PMID 40507333, 2025). "We next assessed whether CDDO-Me promotes the polarization of anti-tumor macrophages in the context of KEAP1 KO cancer CM treatment." (PMID 41462606, 2025). "This is supported by the common incidence of NRF2 activation through Keap1 or NRF2 mutations in human cancers, which further fuels the controversy surrounding whether the anti-cancer effect of SFN can be attributed to its regulation of the NRF2 pathway." (PMID 39961271, 2025). "Our study suggested that KEAP1 and STK11 shared common mechanism in immune regulation, which is associated with enhancement of redox phenotype and the subsequent inhibition of STING/MDA5 expression and the downstream interferon signaling in cancer cells." (PMID 41378285, 2025).
cancer (continued). "The p62/Keap1 signaling pathway is known to be dysregulated in cancer." (PMID 40100373, 2025). "This suggests that the benefit a partial KEAP1-mutant cancer may gain from triterpenoid treatment is likely still superseded by the immune-mediated activation within the microenvironment." (PMID 41462606, 2025). "Research on the mechanism and therapeutic solution in KRAS/KEAP1 mutant cancer is limited, maybe because of the relatively low mutant rate." (PMID 40611261, 2025). "Therefore, targeting NRF2, through strategies like NRF2-siRNA or KEAP1 overexpression, has gained attention as a promising approach to sensitize cancer cells to treatment." (PMID 39935430, 2025). "Like KRAS/LKB1 co-mutation, KRAS/KEAP1 co-mutation is a negative prognostic factor in KRAS mutant cancer." (PMID 40611261, 2025). "PCSK9 inhibition disrupted the p62/Keap1/Nrf2 antioxidant axis, effectively disrupting tumor metabolism, inducing metabolic exhaustion, and increasing cancer cell vulnerability to iron‐induced lipid peroxidation, thus suggesting that anti‐PCSK9 therapy is an effective treatment for liver cancer." (PMID 40145543, 2025). "Furthermore, KEAP1-independent NRF2 control mechanisms should be investigated in relation to cancer treatment and prevention." (PMID 41415550, 2025). "To investigate the influences of the NRF2 activation in 3LL cancer cells on the tumor microenvironment, we challenged transplantation experiments of KEAP1-KO and wild type (WT) 3LL cell lines, taking advantage of the syngeneic immunocompetent nature of 3LL cells toward albino C57BL/6 mouse strain." (PMID 41035689, 2025). "As KEAP1-mutant cancers show reduced tumor immune responses, triterpenoid-mediated immune stimulation may particularly benefit these cases, but this has not been investigated." (PMID 41462606, 2025). "The CRISPR-mediated knockout of KEAP1 nearly eliminated all KEAP1 from the cancer cells." (PMID 41462606, 2025). "The KEAP1/NRF2 pathway regulates the transcriptional output of antioxidant and drug-metabolizing genes and has been implicated in drug resistance across multiple cancers." (PMID 41573641, 2025). "Additionally, they showed that targeting a conserved cysteine residue (C274) in NR0B1 disrupt NR0B1 complexes and impair the anchorage-independent growth of KEAP1-mutant cancer cells." (PMID 40864301, 2025). "Additionally, KEAP1 alterations enable cancer cells to survive oxidative stress by activating the NRF2 antioxidant machinery and collaborating with altered KRAS to promote LUAD development." (PMID 40567251, 2025). "A 2006 study identified mutations in KEAP1 in non-small cell lung cancer (NSCLC), leading to sustained elevated levels of NRF2, and first proposed that NRF2 might contribute to cancer progression and chemotherapy resistance." (PMID 40896440, 2025). "However, MTAP-loss CRC was also associated with a higher frequency of alterations in STK11 and KEAP1, which have been linked to immunotherapy resistance in NSCLC and pan-cancer cohorts." (PMID 38330461, 2024). "The Keap1/Nrf2 pathway is critical for antioxidant responses and cellular defense mechanisms, contributing significantly to tumor progression and resistance to chemotherapy and radiotherapy in different cancer types." (PMID 39050569, 2024). "We show here that KEAP1-mutant cancers promote immunosuppression of the tumor microenvironment." (PMID 38542481, 2024). "This analysis indicates that SY may inhibit FGFR2, EGFR, CAH2, KEAP1, and GSK3β, which are involved in various cellular processes related to cancer development and oxidative stress response." (PMID 38431714, 2024).
cancer (continued). "We posit that because of the broad immunosuppressive phenotype present in KEAP1-mutant cancers, human cancers that develop over a span of years or even decades have equilibrated to the immunosuppressive environment, which is reflected by an overall decrease in macrophages." (PMID 38542481, 2024). "Our data suggest KEAP1 deletion is sufficient to alter the secretion of cytokines, increase expression of immune checkpoint markers on cancer cells, and alter recruitment and differential polarization of immunosuppressive macrophages that ultimately lead to T-cell suppression." (PMID 38542481, 2024). "In summary, a better understanding of the relationship between the activation of the Keap1-Nrf2 signaling pathway in cancer and the overall therapeutic effect, and the mode of interaction and the therapeutic relevance of this interaction, will help to further develop therapeutic drugs." (PMID 38634043, 2024). "Cancer cell lines harboring mutations in KEAP1, a negative regulator of NFE2L2, are typically more resistant to small molecule inducers of ferroptosis than KEAP1 wild-type cell lines." (PMID 39025451, 2024). "Functionally, the best characterized member of this family is KLHL19, encoding KEAP1, a substrate-specific adapter of an E3 ubiquitin ligase complex that controls NRF2 ubiquitination and plays an important role in oxidative stress and cancer." (PMID 39282431, 2024). "Keap1 functions as a negative regulator of Nrf2 and thus may function as a tumour suppressor in cancer cells." (PMID 38794239, 2024). "The natural product hederagenin, a pentacyclic triterpenoid saponin, extracted from various plant herbs has neuroprotective, anti-inflammatory, anti-cancer, anti-lipid peroxidation and oxidative-stress-mitigating properties through the activation of the KEAP1/Nrf2 pathway." (PMID 39334784, 2024). "Consequently, it is crucial to delineate the specific pathways and balance between ROS and NRF2 to comprehend the paradoxical role of the KEAP1/NRF2 pathway in cancer." (PMID 38247494, 2024). "Therefore, it is conceivable that the broad decrease in cytokine release of KEAP1 KO clones is partially responsible for the observed immune-cold microenvironment in human KEAP1-mutant cancers." (PMID 38542481, 2024). "Nevertheless, in terms of tumour cells, it has been acknowledged that the dysregulation of the Keap1-Nrf2 signalling pathway plays a pivotal role in numerous cancers, leading to aberrant Nrf2 activities and oxidative stress disorders, particularly in cases of cervical cancer." (PMID 38732643, 2024). "KEAP1 has been found to be abnormally elevated in many cancers, such as HNSC, LUSC." (PMID 38938386, 2024). "The inhibition of miR-141-3p effectively increased the miRNA expression of Keap1 in cancer cells." (PMID 39308683, 2024). "Finally, we sought to identify a potential mechanism by which Keap1-mutant cancers mediate inflammation and polarization of macrophages." (PMID 38542481, 2024). "Moreover, Nrf2’s interaction with other molecules such as Keap1 also modulates its activity and stability, further influencing cancer progression and resistance mechanisms." (PMID 39286246, 2024). "Given the pivotal position NRF2 occupies in chemoprevention and cancer therapy, the activation of the NRF2/KEAP1 signaling pathway in cancer cells often results in chemoresistance, neutralizing drug-induced oxidative stress, and shielding cancer cells from drug-mediated cell death." (PMID 38403250, 2024). "Finally, we propose that prostaglandin release by KEAP1 KO cancer cells warrants further investigation as a mechanism for driving T-cell suppression and polarization of immunosuppressive macrophages." (PMID 38542481, 2024). "However, SMURF1 increases KEAP1 degradation to induce Nrf2 axis for reducing ER stress and this can be further evaluated in the treatment of cancer." (PMID 39286246, 2024).